MAPK9 (mitogen-activated protein kinase 9)
Diseases named in the same sentence as MAPK9 in open-access papers (continued):
Sharing a sentence is not in itself a finding about the gene and the disease.
psoriasis (3 papers, 2020 to 2024). An autoimmune condition characterized by red, well-delineated plaques with silvery scales that are usually on the extensor surfaces and scalp. "We demonstrated a potential relationship between DUSP1 and miR-34a; DUSP4 and miR-34a, miR-382, and miR-3188; MAPK9 and miR-1275, MAP2K7 and mir-200-5p; MAP3K2 and mir-200-5p, which may be the subject of further research in the context of psoriasis." (PMID 38445655, 2024). "Nevertheless, we demonstrated a potential relationship between DUSP1 and miR-34a; DUSP4 and miR-34a, miR-382, and miR-3188; MAPK9 and miR-1275, MAP2K7 and mir-200-5p; MAP3K2 and mir-200-5p, which may be the subject of further research in the context of psoriasis." (PMID 38445655, 2024).
cardiac arrhythmias (2 papers, 2023). Any disturbances of the normal rhythmic beating of the heart or MYOCARDIAL CONTRACTION. "XFPC may regulate autophagy by down-regulating the expression of CSF1, MAPK9, MAP3K7, and AKT3, thus achieving the purpose of treating chronic obstructive pulmonary disease." (PMID 37274101, 2023).
colorectal adenoma (2 papers, 2013 to 2015). An adenoma that arises from the colon or rectum. "Most interestingly, in the Gaspar Colon colorectal adenoma dataset Bcl6 expression was significantly positively correlated with MAPK9, MAP2K4 and Yes1, and negatively with Dlg2, relative to normal intestinal mucosa." (PMID 26187947, 2015).
colorectal tumor (2 papers, 2015 to 2025). "A significant association was found between MAP2K7 and MAPK9 expression and the histological grade of colorectal tumors." (PMID 41515982, 2025).
COVID-19 (2 papers, 2021 to 2024). A disease caused by infection with severe acute respiratory syndrome coronavirus 2. "Studies have also shown low levels of MAPK9 in COVID-19 patients, suggesting its role in the induction and development of the inflammatory process regardless of the type of disease." (PMID 38445655, 2024).
influenza (2 papers, 2015 to 2016). An acute viral infection of the respiratory tract, occurring in isolated cases, in epidemics, or in pandemics; it is caused by serologically different strains of viruses (influenzaviruses) designated A, B, and C, has a 3-day incubation period, and usually lasts for 3 to 10 days. "Of the proteins with reduced expression identified in our study, the five most-reduced DEPs in samples from influenza-infected patients that were also correlated with higher viral loads were CTSD, KLK7, MFGE8, MAPK9 and CD27, respectively." (PMID 27088501, 2016).
oral cancer (2 papers, 2020 to 2022). "MAPK9 is a tumor suppressor in oral cancer, emphasizing its positive role in apoptosis." (PMID 32831648, 2020).
rheumatoid arthritis (2 papers, 2023 to 2025). A chronic, systemic autoimmune disorder characterized by inflammation in the synovial membranes and articular surfaces. "According to the results of molecular docking, in the context of rheumatoid arthritis, phytocannabinoids may bind to important target proteins such as PIK3CA, AKT1, MAPK9, PRKCD, BRAF, IGF1R, and NOS3." (PMID 36983855, 2023).
type I diabetes (2 papers, 2022). "LINC02086- hsa-miR-17-5p- MAPK9/WEE1 and LINC00960-hsa-miR-107-INSIG1, in association with the type I diabetes." (PMID 36440209, 2022).
anaplastic large cell lymphoma (1 paper, 2023). Anaplastic large cell lymphoma (ALCL) is a rare and aggressive peripheral T-cell non-Hodgkin lymphoma, belonging to the group of CD30-positive lymphoproliferative disorders, which affects lymph nodes and extranodal sites. "Other FRK‐related fusion genes, including CAPRIN1::FRK, PABPC1::FRK, and MAPK9::FRK, have been identified in ALK‐negative anaplastic large cell lymphoma (ALCL)." (PMID 37601849, 2023).
chordoma (1 paper, 2022). Chordomas are rare malignant tumors arising from embryonic remnants of the notochord in axial skeleton. "Although the molecular mechanisms by which TMED3 promotes chordoma progression are not fully understood, evidence shows that TMED3 plays these functions through activating PI3K/AKT signaling and inhibiting apoptosis and MAPK9/JNK2 signaling pathways." (PMID 35805075, 2022).
endometriosis (1 paper, 2025). The growth of functional endometrial tissue in anatomic sites outside the uterine body. "Furthermore, IL6ST facilitated progression of endometriosis by activating mitogen-activated protein kinase 9/Signal Transducer and Activator of Transcription 3 signaling pathway." (PMID 39821173, 2025).
myelofibrosis (1 paper, 2022). A partial or complete replacement of the bone marrow stroma by fibrous tissue. "To determine whether JNK1 or JNK2 selectively contributes to TGF-β–induced myelofibrosis, we used CRISPR/Cas9 gene editing to delete Mapk8 (JNK1) or Mapk9 (JNK2) in MSCs." (PMID 35439167, 2022).
Nephropathy (1 paper, 2020). A nonspecific term referring to disease or damage of the kidneys. "Previous studies for microRNA-451 revealed an early increase in its level in the tissue of the kidney and later on a decrease in urine, reflecting the increased activity of signal pathways such as MAPK9 and SMAD3 in association with the process of nephropathy development." (PMID 32855824, 2020).
scrapie (1 paper, 2014). A fatal disease of the nervous system in sheep and goats, characterized by pruritus, debility, and locomotor incoordination. "MST1, DLK and mitogen-activated protein kinase 9 (JNK2) (p54; α2/β2 isoforms), which clustered together because they were expressed to similarly lower levels in scrapie- than in mock-infected mice at 130 dpi, are all involved in an MST1 signaling pathway that promotes neuronal death." (PMID 25183307, 2014).
small cell lung carcinoma (1 paper, 2006). Small cell lung cancer (SCLC) is a highly aggressive malignant neoplasm, accounting for 10-15% of lung cancer cases, characterized byrapid growth, and early metastasis. "Small cell lung cancer exhibited increased expression of MRP5, activation of Wnt pathway inhibitors, and upregulation of p38 MAPK activating genes, while NSCLC showed downregulation of CDKN2A, and upregulation of MAPK9 and EGFR." (PMID 16705311, 2006).
cancer (116 papers, 2007 to 2025). A tumor composed of atypical neoplastic, often pleomorphic cells that invade other tissues. "Moderate expression of MAPK9 protein was observed in cancer tissue, while high expression was observed in normal tissue." (PMID 41515982, 2025). "After assessing the mRNA expression levels of selected genes, we assessed the expression of MAP2K4, MAP2K7, MAPK8, and MAPK9 proteins in cancer and normal colon tissue using images from the Human Protein Atlas." (PMID 41515982, 2025). "As a member of MAPK protein family, MAPK9 plays a part in multiples signals of mammalian cells and is found improperly activated or inactivated in cells of different cancer types." (PMID 35854294, 2022). "The results showed that ALOX12, ANGPTL7, DRD4, and MAPK9 remarkably decreased within ESCC samples relative to non-carcinoma samples, whereas SLC38A1 and ZNF419 were highly expressed." (PMID 34291083, 2021). "Genes MAP 3 K2, MAP 3 K7, MAP 3 K18, MAPK8 and MAPK9 in the pathway, which were responsible for DNA damage or apoptosis, were all upregulated by melatonin treatment in four cancer cell lines." (PMID 32689938, 2020). "Somatic mutations in genes within narrow MCR, including FLT4, MAPK9, SPO11 and KHDRBS2, have been reported in cancers (COSMIC v48 release)." (PMID 21151896, 2010). "The higher expression of MAPK9 observed in lower-grade tumors (G1/G2) may indicate a protective or adaptive role of MAPK9 in the early stages of cancer." (PMID 41515982, 2025). "This gene is particularly studied in cancer, where, depending on its type, MAPK9 may act as both a tumor suppressor and inducer." (PMID 38445655, 2024). "However, the expressions of CUL3, GSK3B, KEAP1, and MAPK9 showed positive relationship with RNAss in various cancers." (PMID 35242279, 2022). "It is worth noting that IKBKB, APOB and MAPK9 are not only vital cholesterol metabolism regulation genes but are also often upregulated in cancer, which implies that the use of cholesterol-lowering drugs in HNSCC patients with the overexpression of these genes may be helpful." (PMID 37568192, 2023). "MAPK9, also known as JNK2, interacts intricately with several key signaling pathways, significantly impacting cellular processes and cancer biology." (PMID 38994962, 2024). "Two important ASEs were located in MAPK9 (JNK2) and STRA13, which have been well studied as key genes in cell proliferation in cancers." (PMID 34290732, 2021). "Western blot analysis also showed that knockdown of POLE2 inhibited the expression levels of Cancer-related pathway proteins including p-Akt, CCND1, MAPK9, and PIK3CA." (PMID 33644060, 2021). "Western blot analysis also showed that knockdown of POLE2 inhibited the expression levels of cancer-related pathway proteins including p-Akt, CCND1, and PIK3CA, while the expression of MAPK9 was promoted." (PMID 33644060, 2021). "These miRNAs target the tumour suppressor genes, PTEN, TP53INP1 and TP53INP2, and other proteins involved in cancer development and progression, such as BCL2L2, ERBB4, MAPK9, MCL1, MYCN, VEGFA and VEGFR1." (PMID 20668671, 2010). "MAP2K7 and MAPK8 may promote disease progression and metastasis, whereas MAPK9 and MAP2K4 may be more protective at certain stages of cancer development." (PMID 41515982, 2025).
tumor (113 papers, 2001 to 2025). "Both, proapoptotic BCL-2 or MAP kinase pathway members (BIK, BAK1, MAP3K12, and MAPK9) and proliferation-associated tumor drivers (FOS, HOXA3, and POLR2B) had an increased gene expression." (PMID 35778418, 2022). "Data from the Human Protein Atlas revealed differential protein expression of MAP2K4, MAP2K7, MAPK8, and MAPK9 between tumor and normal colon tissues; notably, MAPK8 protein expression did not correspond to the mRNA-level findings." (PMID 41515982, 2025). "Studies have shown that MAPK9 presents overexpression in a variety of tumors and promotes tumor progression." (PMID 41105646, 2025). "MAPK9 has been shown to promote tumor growth by stabilizing MYC and facilitating proliferative signaling—key features of the CMS2 subtype." (PMID 41515982, 2025). "Patients with low MAP2K4, MAP2K7 or MAPK8 expression or high MAPK9 or JUN in their tumours had greater metastatic frequency following tamoxifen treatment." (PMID 40826108, 2025). "Conversely, MAPK9 gene expression tended to be higher in tumor tissues with lower histological grades." (PMID 41515982, 2025). "Circ_MAPK9 expression on the microarray of tumor from clinical HCC patients was detected by in situ hybridization (ISH)." (PMID 38163874, 2024). "The results displayed that the growth of xenograft tumors from circ_MAPK9 knockdown cells was slower and tumor size was smaller compared to tumors grown from the corresponding control cells." (PMID 38163874, 2024). "Consistent with our findings, reverted tumours showed upregulated expression of MAPK9 expression, a negative regulator of JUN." (PMID 29662623, 2018). "Interestingly, when tumor samples from several of the CONKO-005 trial participants were re-analyzed, a subgroup of patients with a combination of SMAD4 loss and low Mitogen-Activated Protein Kinase 9 (MAPK9) expression benefited from the addition of Erlotinib." (PMID 34778259, 2021). "These combined results indicate that RGB-286638 may delay tumor growth, possibly by its MAPK9 and CDK inhibitory properties." (PMID 33392504, 2020). "MAPK9 encodes one of the JNK isoforms, which may exhibit different functions depending on the development of the tumor—for example, in some cases, JNK activation may lead to apoptosis of tumor cells, while in others it may lead to cell survival." (PMID 41515982, 2025). "Furthermore, bioinformatics analysis confirmed that MAP2K7 and MAPK8 appear to promote tumor aggressiveness and metastasis, whereas MAPK9 and MAP2K4 may have a protective or regulatory role in early stages of the disease." (PMID 41515982, 2025). "The up-regulation of RELA, AKT1, TLR1 and RAF1 and the down-regulation of MAPK9 and MAP3K8 were determined by RT-qPCR, indicating that the enhanced anti-tumor function may associate with T cell immune response and proliferation related Toll-like receptor-Akt-NF-κB signaling pathway." (PMID 35046962, 2021). "MAPK9 (JNK2), a member of the JNK kinase family, is known for its tumor‐suppressive and apoptotic functions." (PMID 40186402, 2025). "As miR-642b-3p is the downstream target gene of circ_MAPK9, we then examined the expression of miR-642b-3p in 41 pairs of HCC samples by qRT-PCR, and found that miR-642b-3p expression decreased in HCC tumor tissues compared to that in adjacent normal tissues (P < 0.05)." (PMID 38163874, 2024).
infection (38 papers, 2004 to 2026). The state of being infected such as from the introduction of a foreign agent such as serum, vaccine, antigenic substance or organism. "In addition, the expression of MAPK7 and MAPK9 was significantly upregulated in the resistant grape plant cultivar following P. viticola BS-4-MW infection, but was downregulated in the susceptible cultivar." (PMID 35572700, 2022). "Interestingly, MAPK9 appears to support VACV infection but resist VACV-A4L infection; moreover, it was found to decrease Simian viru s 40 (SV40) infection while increasing Human cytomegalovirus (HCMV) strain AD169 replication." (PMID 35918371, 2022). "The kinase-substrate phosphomotif pattern analysis revealed several kinases, including EEF2K, HASPIN, MAPK9, MAST2, and Spleen tyrosine kinase (SYK), that can phosphorylate multiple NiV proteins at various sites, suggesting regulatory roles during infection." (PMID 41424949, 2025). "We next analyzed the protein-protein interaction network even further and demonstrated that the infection related proteins STAT3, AKT1, MAPK9, MAPK14, and CREBBP had the highest degree of connectivity among DAPs." (PMID 36262184, 2022). "A few genes were downregulated 4 h after infection: caspase 8 (Casp8), nuclear receptor subfamily 2, group C, member 2 (Nr2c2/TAK1), mitogen-activated protein kinase 9 (Mapk9/JNK2) and interleukin 6 receptor-alpha (Il6ra)." (PMID 30555476, 2018). "Also, the STAT3, AKT1, MAPK9, MAPK14, and CREBBP were identified as host’s infection response regulators of bacterial Hcp in duck." (PMID 36262184, 2022).
heart disease (1 paper, 2025). "CAMK2D is linked to heart disease, and MAPK9/10 are involved in inflammation, apoptosis, and proliferation." (PMID 41257548, 2025).
MAPK9 also shares sentences with these, for which no sentence is quoted: Obesity (27 papers); ovarian carcinoma (16); leukemia (12); Alzheimer disease (8); atherosclerosis (8); cardiac hypertrophy (7); Hyperglycemia (7); asthma (6); breast tumor (5); cervical cancer (5); liver cancer (5); liver fibrosis (5); multiple myeloma (5); Arthritis (4); cyst (4); injury (4); Liver disease (4); nasopharyngeal carcinoma (4); Parkinson disease (4); renal fibrosis (4); Sepsis (4); skin cancer (4); squamous cell carcinoma (4); acute myeloid leukemia (3); bacterial infection (3); cardiovascular disease (3); cholangiocarcinoma (3); diabetic cardiomyopathy (3); glaucoma (3); Hypertension (3).
A further 103 diseases each share a sentence with MAPK9 in 3 papers or fewer.